AQP1 (aquaporin 1 (Colton blood group))
Diseases named in the same sentence as AQP1 in open-access papers (continued):
Sharing a sentence is not in itself a finding about the gene and the disease.
cancer (continued). "It has been suggested that increase of lactate induces ICF acidification and promotes excess H+ extrusion into the ECF (probably together with water), thus providing an important function for AQP1 upregulation in cancer cells." (PMID 27367682, 2016). "The importance of AQP1 in determining malignancy of cancer cells is also confirmed by the observation that some AQP1 polymorphisms can be used as survival prognosis factors in patients with GBM." (PMID 27367682, 2016). "AQP1 is thus proposed as a key player in cancer biology and a potential target for drug development." (PMID 25886458, 2015). "Cancer cells with AQP1 over-expression had stronger capacity of cell migration, invasion, and metastasis." (PMID 25886458, 2015). "In addition to their transport activity, the overexpression of AQP1, AQP3 and AQP5 in cancer has been associated with signal transduction pathways and cytoskeleton reorganization, resembling mechanisms typically mediated by receptors." (PMID 39941100, 2025). "In cancer cells, AQP1 has been proposed to be upstream of the Bcl‐2 pathway." (PMID 39175041, 2024). "Researchers have speculated that the role of AQP1 in stabilizing the cadherin/ Lin-7/−catenin /F-actin complex enhances the invasive and migratory potential of cancer cells." (PMID 38336645, 2024). "In vivo studies further revealed that AQP1 promoted cancer cell extravasation and lung metastases." (PMID 37762642, 2023). "Understanding AQP1’s multifaceted role in these processes could thus offer crucial insights for the development of new therapeutic strategies targeting cancer metastasis." (PMID 37762642, 2023). "Results here showed the invasiveness of EC cells relies on AQP1 ion channels, and pharmacological inhibition of these channels could be a new strategy to limit motility in resistant cancer types." (PMID 37760476, 2023). "AQP1 KO mice analysis revealed the increased migration of endothelial cells alongside vascular growth, which has implications for increased AQP1 expression in the endothelia of malignant tumors." (PMID 36675000, 2023). "Interestingly, AQP1 overexpression has been documented in a variety of human cancers, including those of the biliary duct, bladder, brain, breast, cervix, colon, lung, nasopharynx, and prostate." (PMID 37762642, 2023). "Of note, at least four AQPs (AQP1, AQP3, AQP4, and AQP9) have been shown to modulate the activity of specific MMPs, which appears to be a key mechanism underlying the promotion of cellular local invasion and cancer cell metastasis by AQPs." (PMID 35847914, 2022). "In the case of SOD3 and AQP1, their expression was significantly altered in G2 and G3 cancer." (PMID 36555458, 2022). "Interestingly, being under-represented in TNBC cells, AQP3 played a more important role in CAP-induced anti-cancer efficacies than AQP1 that was over-expressed in these cells." (PMID 35637961, 2022). "AQP1 has been shown to regulate the migration of many types of cancer cells." (PMID 33125833, 2021). "In addition, AQP1 is overexpressed in various human cancers, including biliary duct, bladder, breast, cervix, lung, prostate, nasopharynx, and brain cancers." (PMID 32253832, 2020). "Therefore, more studies are needed to explore the specific roles and mechanisms of AQP1 in different types of cancer." (PMID 32373535, 2020). "AQP1, 5, and 9 expression was significantly higher in malignant tumors than in benign tumors." (PMID 33271827, 2020). "However, the overexpression of AQP1 in cancer tissue resulted in strong migration, invasion and metastasis of cancer cells to other organs." (PMID 33271827, 2020). "Rg3 has stereoselective anti-cancer effects in the AQP1 high-expressing cell line MDA-MB-231." (PMID 31374984, 2019). "The overall distances travelled were greater in SW480 than HT29 cells, illustrating an inherently higher two-dimensional migration velocity with a low sensitivity to AQP1 modulators, indicating mechanisms other than AQP1 can enable motility in some cancer lines." (PMID 31477744, 2019).
cancer (continued). "Inhibition of the AQP1 ion channel reduced cancer cell invasiveness." (PMID 31477744, 2019). "Combined AQP1 inhibitors could act on target cells (such as migrating cancers) that require both the AQP1 water and ion channel activities, while minimizing side effects on other cells and tissues by being applied at lower concentrations." (PMID 31477744, 2019). "It is already known that AQP1 is involved in the chemotactic migration of the cancer cells." (PMID 31374984, 2019). "In further human studies, pharmacological inhibition of AQP1 may have utility in cancer therapy, whereas AQP1 induction might accelerate wound healing and facilitate organ regeneration." (PMID 31023968, 2019). "Future work might identify signals that induce trafficking of intracellular AQP1 to the membrane, and alter motility in cancer lines." (PMID 31477744, 2019). "We report here the proof of concept that AQP1 inhibition is also able to strongly reduce cell's ability to metastasize by crossing endothelial barrier and further support AQP1 as proangiogenic protein and potential target for cancer therapy." (PMID 29044946, 2018). "An ingenuity pathway analysis (IPA) showed that “Cancer” was the top-ranked disease and that “Cellular Movement”, “Cellular Development”, and “Cellular Growth and Proliferation” were some of the top-ranked biological functions related to the depletion of AQP1." (PMID 30042826, 2018). "A deeper understanding of AQP1 mechanisms in cancer cells could lead to the development of novel therapeutic strategies in ESCC." (PMID 30042826, 2018). "AQP1 was primarily located in the cytoplasm and/or the nuclear membrane of carcinoma cells." (PMID 30042826, 2018). "Previous research has demonstrated that AQP1 may be anideal therapeutic target for restoring salivary gland function in cancer patients receiving ionizing radiation treatment." (PMID 29340084, 2017). "This has prompted researchers to evaluate the link between AQP1 and cancer biological functions." (PMID 28146084, 2017). "Clinical utility of AQP1 inhibitors may apply to other types of cancer that are known to over-express this transmembrane protein." (PMID 28146084, 2017). "High cytoplasmic expression of AQP1 indicated shorter cancer-specific OS and PFS." (PMID 26812884, 2016). "Considering the number of studies reporting the consistent implication of AQP1, AQP3 and AQP5 in the development of multiple cancer types and their strong association with signaling pathways, this review is focused on the critical roles of these AQPs as transceptors involved in cancer progression." (PMID 39941100, 2025). "Furthermore, AqB007 and AqB011 could selectively block the AQP1 ion channel conductance and slow cancer cell migration." (PMID 36803413, 2023). "An increase in AQP1 expression levels with increasing cancer grade, coupled with plasma membrane localization, upregulation by estradiol, and inhibition of invasiveness by AQP1 ion channel blockers, converge on the interesting proposal that AQP1 ion channel function is important for EC progression." (PMID 37760476, 2023). "Moreover, taking into account that AQPs have been implicated in various cancers, it is tempting to speculate that FAK, ß-catenin and LIN-7 may interact with other AQPs besides AQP1, including AQP5, as suggested by indirect experimental evidence." (PMID 36077012, 2022). "Therefore, effective regulation of AQP1 plays an important role in the treatment of cancers." (PMID 36532729, 2022). "In contrast, bacopaside II surprisingly enhanced cancer cell invasion in both cell lines, suggesting this agent is likely to have multiple targets of action, and that its side effects are mediated at least in part at a level upstream of AQP1-dependent signalling." (PMID 31477744, 2019). "Furthermore, AQP1 is a plausible novel therapeutic target and may enable development of effective cancer therapeutics." (PMID 28146084, 2017).
cancer (continued). "However, a strongly positive staining of AQP1 in the cytoplasm of cancer cells could be observed in IDC." (PMID 26812884, 2016). "This review explores the pivotal roles of AQP1, AQP3 and AQP5 as transceptors in cancer biology, underscoring their importance as pharmacological targets." (PMID 39941100, 2025). "In colorectal cancer progression, AQP1 and AQP5 expression was found to be induced in the early stage of the disease and maintained stability through the late stage of cancer development." (PMID 39941100, 2025). "MAP1LC3A, AQP1, and AP1S1 were consistently amplified across cancer types whilst XAF1, CASP3, and SNCA exhibited copy deletions." (PMID 38642129, 2024). "According to recent research, the expression of AQP1 had been detected in biliary tract carcinoma (BTC), and its levels decreased as the carcinoma progresses in terms of invasion." (PMID 37904849, 2023). "For CSS, patients with cancer-specific death presented higher expression patterns of RGPD8, BAIAP2L1, and DDX11 and lower expression patterns of SLC16A9, FRAS1, AQP1, TMEM38B, and PRUNE2, in both the univariate and multivariate analyses." (PMID 31963294, 2020). "The AQP1 and AQP4 water channel blocker AqB013 also slowed cancer cell migration, suggesting that both AQP1 water and ion channel functions are involved in facilitating cell mobility." (PMID 29099773, 2017). "This research showed that AQP1 and HIF-1α could be selected as potential targets for cancer therapy and cellular senescence." (PMID 40011266, 2025). "So far, studies of AQP1, AQP3, and AQP5 involvements in many different cancer types are performed on the basis of numerous cell line, in vivo mice model, and expression profiles of these AQPs in resected cancer tissue samples." (PMID 35847914, 2022). "Overall, several AQPs, including AQP1, AQP3, AQP4, AQP5, AQP8, and AQP9, have been suggested to transport H2O2, and their expression promotes cancer cell growth and migration, However, solid data exist only for AQP3- mediated H2O2 transport as one of the key mechanisms for cancer cell migration." (PMID 35847914, 2022). "AQP1 can interact with Lin7/β-catenin or FAK and regulate cancer cell migration." (PMID 32814878, 2021). "It is worth noting that drugs affecting AQP1 expression are not currently used for cancer treatment." (PMID 32373535, 2020). "Aquaporin-1 (AQP1) has been proposed as a dual water and cation channel that when upregulated in cancers enhances cell migration rates; however, the mechanism remains unknown." (PMID 31477744, 2019). "We therefore hypothesised their anti-cancer potential when combined, given that separately we have shown they reduced the migration of CRC cell lines that expressed high levels of AQP1." (PMID 31574930, 2019). "Kourghi and colleagues showed AqB011 selectively inhibited migration in AQP1-expressing cancer cell lines, but not in those without AQP1, demonstrating that the AQP1 ion conductance can serve an essential role in cellular functions such as migration." (PMID 29755973, 2018). "However, this contrasts with studies showing that AQP1 and AQP4 have been shown to promote cancer metastasis through their role in endothelial cell migration and angiogenesis." (PMID 28036023, 2016). "AQP1 has previously been shown to be involved in cell cycle control, suggesting that AQP3 may also have a role in the progression of cancer." (PMID 16001974, 2005). "Furthermore, overexpression of AQP1 in mouse cancer cell lines B16F10 and 4T1 did not lead to increased proliferation, although it did result in enhanced extravasation and metastases." (PMID 37762642, 2023). "Data here suggest that non-NMDA receptors and AQP1 channels might serve complementary roles in enhancing invasive cancer activity, since blocking both was generally more effective than blocking either alone." (PMID 36831372, 2023). "Whether AQP1 and FAK also interact in cancer cell migration remains to be tested." (PMID 29922644, 2018).
cancer (continued). "Moreover, AQP1 was localized mainly in vessels and microvessels, not in cancer cells." (PMID 33271827, 2020). "Kourghi and colleagues further deepen this narrative by showing that certain AQP1 ion channel blockers, which do not impact AQP1’s water channel activity, effectively inhibited the migration of HT29 cancer cells." (PMID 37762642, 2023). "Finally, accordingly to previous observations regarding the relationship between AQ1 and patient outcome in carcinomas of different sites, such as ovary, lung, prostate, brain, and breast, we have documented a sensible trend for better survival in patients with negative AQP1 immunoexpression." (PMID 33807998, 2021).
infection (19 papers, 2013 to 2025). The state of being infected such as from the introduction of a foreign agent such as serum, vaccine, antigenic substance or organism. "We can only speculate whether the inflammation of the appendix leads to an increase of APQ1, or a primary up-regulation of AQP1 in the appendix leads to an increase of intestinal wall permeability and susceptibility to bacteria transgression and organ infection." (PMID 28762291, 2017). "The altered expression in Aqp1 and Aqp5 represents physiological and pathological changes in the lungs exposed to radiation or infection." (PMID 40141336, 2025). "Additionally, loss of AQP1 level was also observed during hypoxic conditions, suggesting that hypoxia may also be a major event in the lung post-infection." (PMID 35712703, 2022). "While AQP1 levels are increased generally in most organs, its level decreased in the lung during other infections." (PMID 35712703, 2022). "The recruitment of Na+/glucose cotransporter (SGLT1) and aquaporin 1 (AQP1) to the site of infection contributes to this actin-dependent cellular invasion." (PMID 35099276, 2022). "The transcriptome of the tubular epithelial- and podocyte-specific genes, AQP1, AQP6, NPHS2, SCL12A1, was examined over a period of 11 days for toxic and ischemic and of up to 24 days for nephritic and infection-associated AKI." (PMID 36285332, 2022). "We showed that ART4 and AQP1 coalesce in proximity to the parasite entry site upon invasion, suggesting an infection-dependent remodeling of erythrocyte membrane microdomains." (PMID 34880413, 2021). "In experimental mice model, Herpes simplex virus (HSV) decreased AQP4 in the acute phase of infection but increased its expression along with AQP1 in the long-term infection." (PMID 33796134, 2021). "Brain organoid studies also hinted at the mechanism of infection, showing tropism of viral particles toward aquaporin-1 (AQP1)-positive cells which may have represented ChP cells." (PMID 34250020, 2021). "In addition, a study showed that AQP1 expression is induced in leukocytes in septic patients and is highly expressed during septic shock, demonstrating that AQP1 is involved in regulating the immune response during infection." (PMID 31529146, 2019). "Therefore, it is considered that the protective effects of HES 130/0.4 on endothelial barrier dysfunction and high epithelial permeability after uncontrolled HS and infection, to some extent, in part by upregulating the expression of AQP1 and AQP5." (PMID 23741323, 2013). "The theoretical significance of the herein demonstrated induction of Aqp1 may be to enhance the neutrophil’s ability to migrate to sites of infection." (PMID 24028651, 2013). "The current experiment showed that in a rat two-hit model of hemorrhagic shock and infection, the decreased expressions of AQP1 and AQP5 may play an important role in acute lung injury." (PMID 23741323, 2013). "The fluid resuscitations with hydroxyethyl starch may be the better choice for preventing ALI after severe HS and infection, in part by up-regulating the expressions of AQP1 and AQP5." (PMID 23741323, 2013). "Human Norovirus (HNoV) infection leads to the shortening of microvilli, compromising the epithelial barrier.VP1 further promotes the production of AQP1, which increases intestinal barrier permeability." (PMID 39767680, 2024). "Our present study illustrated that, in a rat model of uncontrolled HS and infection, resuscitation with HES 130/0.4 significantly attenuated the HS-induced decreased expression of AQP1 and AQP5 in the lung tissues." (PMID 23741323, 2013). "In contrast, the expression of AQP1 was not affected by the enterovirus EV71, although its infection can cause diarrhea." (PMID 35458572, 2022).
kidney disease (17 papers, 2014 to 2024). "After the discovery of AQP1, successive studies had explored the role of AQP1 in kidney disease, and finally found that the protein level of AQP1 in urine can be used as a diagnostic indicator for early-stage ccRCC." (PMID 35245343, 2022). "Several reports indicate that alterations of AQP-1, − 2, − 4 and − 5 expression are highly associated with renal diseases." (PMID 33663503, 2021). "Collectively, these findings suggest that the loss of AQP1 may trigger proximal tubule injury, thus accelerating the progression of kidney disease as we observed in the adenine-induced CKD model." (PMID 38542420, 2024). "Aquaporin 1 (AQP1)-expressing renal tubules (green) from various kidney diseases all exhibited significant damage compared to control renal tubules." (PMID 36869030, 2023). "Upregulation of glomerular AQP-1 is found in all forms of human renal diseases, probably due to compensation for losing cellular integrity." (PMID 33663503, 2021). "AQP1 in red blood cells is downregulated in some renal diseases, which is relevant to the imbalance of the vascular system and endothelial cells such as uremic syndrome." (PMID 25815318, 2015). "Notably, exosomal proteins such as aquaporin-1 (AQP1) and aquaporin-2 (AQP2) have been discovered as possible kidney disease biomarkers." (PMID 39728069, 2024).
bacterial infection (4 papers, 2005 to 2020). "Accordingly, AQP1 ablation in macrophage is associated with a strong reduction of IL1β release and neutrophilic inflammation as confirmed by our in vivo data showing a major effect during bacterial infection." (PMID 25719758, 2015). "However, under stress and bacterial infection (e.g., Fusobacterium) conditions, AQP1, AQP3, AQP8, and AQP10 are mainly responsible for the maintaining of water homeostasis in the gastrointestinal tract." (PMID 32565721, 2020).
cardiovascular disease (4 papers, 2018 to 2024). "In view of potential new roles of AQP1 in cardiovascular homeostasis, agonists and antagonists of AQP1 are being developed their use in cardiovascular diseases associated with heart and vessel remodeling, like treating hypertrophic cardiac remodeling or microcardia." (PMID 31023968, 2019). "Notably, AQP1 was also reported to transport NO, the main anti-atherogenic molecule that plays a key role in the protection against the onset and progression of cardiovascular disease." (PMID 29301341, 2018). "Together, our studies identify AQP1 as a novel epigenetic regulator of HDAC4-Mef2A-dependent EC senescence and angiogenic potential, highlighting its potential as a therapeutic target for antagonizing age-related cardiovascular diseases." (PMID 39180980, 2024).
neurological disorders (4 papers, 2010 to 2021). "For the 30 exclusive DEG for BAHN overlap, AQP1 (Aquaporin 1 Colton Blood Group) is a water channel molecule that is expressed in the central nervous system and was previously related to neurodegenerative and neurological disorders." (PMID 30645614, 2019). "Moreover, in some neurological disorders, i.e., MS, there is increased expression of AQP1 and AQP4 in the brain, probably due to the need to maintain water homeostasis." (PMID 26950113, 2016). "Water channel proteins, known as aquaporins (AQPs), notably AQP-1 and AQP-4, appears to be involved in the pathophysiology of several neurological diseases." (PMID 20969805, 2010).